ACTL8 (actin like 8)
Synonyms: CT57
Tractability: PROTAC: ubiquitination databases record sites on it.
Gene: Protein-coding gene on chromosome 1 (17,755,333 to 17,827,063, forward strand). Ensembl gene ENSG00000117148.
Subcellular location: Cytoplasm, cytoskeleton
Subcellular location (Human Protein Atlas): Cytosol
Gene Ontology:
Molecular function: protein binding; protein kinase binding; structural constituent of postsynaptic actin cytoskeleton
Biological process: epithelial cell differentiation; axonogenesis; cell motility; postsynaptic actin cytoskeleton organization
Cellular component: actin cytoskeleton; actin filament; axon; cytoplasm; membrane; NuA4 histone acetyltransferase complex; synapse; cytoskeleton
Genetic constraint (gnomAD): Loss-of-function variants: 4 observed, 12.1 expected, observed/expected ratio (o/e) 0.33, 90% interval 0.16 to 0.76. The upper end of that interval is the gene's LOEUF score, 0.76, which puts it in group 3 of 6, group 1 being the genes least tolerant of losing a copy. Missense variants: 381 observed, 503.65 expected, observed/expected ratio (o/e) 0.76, 90% interval 0.69 to 0.82. Synonymous variants: 224 observed, 213.23 expected, observed/expected ratio (o/e) 1.05, 90% interval 0.94 to 1.17.
Homologues: Orthologues: chimpanzee ACTL8 (99% identical), macaque ACTL8 (98% identical), dog ACTL8 (78% identical), pig ACTL8 (74% identical), guinea pig ACTL8 (64% identical). Paralogues in human: ACTA2 (32% identical), ACTC1 (32% identical), ACTG1 (32% identical), ACTG2 (32% identical), ACTA1 (32% identical), ACTB (32% identical), ACTR1A (31% identical), ACTR1B (31% identical), ACTRT3 (31% identical), ACTR2 (30% identical), ACTBL2 (30% identical), ACTRT2 (30% identical), and 14 more.
Diseases named in the same sentence as ACTL8 in open-access papers:
ACTL8 is named in the same sentence as 12 diseases in open-access papers, as found by Europe PMC text mining. Sharing a sentence is not in itself a finding about the gene and the disease. The quoted sentences say what the papers report.
breast carcinoma (6 papers, 2019 to 2025). "Research has indicated that ACTL8 is linked to a poor prognosis in glioblastoma and breast cancer." (PMID 39857819, 2025). "Only 3 tumor-reactive circulating CD8 T cell lines showed responses, which were limited to two CTA (PLAC1 and ACTL8) overlapping peptide pools, reiterating the challenge of finding relevant breast cancer antigens." (PMID 40730190, 2025). "Our study constructed the prognostic signature based on breast cancer PD-1/PD-L1 pathway molecular typing-related genes (IFNG, JCHAIN, ELOVL2, PIGR, PAGE5, ACTL8, and CLEC3A)." (PMID 37154982, 2023). "Like CT83, also Actin like 8 (ACTL8) is already described as a potential target in breast cancer and is, to our knowledge, absent from current immunotherapy development as well." (PMID 31069014, 2019).
triple-negative breast carcinoma (2 papers, 2019 to 2023). An invasive breast carcinoma which is negative for expression of estrogen receptor (ER), progesterone receptor (PR), and human epidermal growth factor receptor 2 (HER2). "ACTL8 was up-regulated in triple-negative breast cancer and was associated with poor prognosis." (PMID 37154982, 2023). "ACTL8 is highly expressed in 57% of the analyzed triple-negative breast cancer samples and potential side effects on an immunotherapy is only predicted for colon with a very low expression level." (PMID 31069014, 2019).
Azoospermia (1 paper, 2023). Absence of any measurable level of sperm,whereby spermatozoa cannot be observed even after centrifugation of the semen pellet. "Expression of ACTL8 has been reported to be isolated to the testes following a study that undertook exome sequencing in males with non-obstructive azoospermia, a condition where no sperm is present in an ejaculate due to failures during spermatogenesis." (PMID 37508063, 2023).
colorectal cancer (1 paper, 2025). A primary or metastatic malignant neoplasm that affects the colon or rectum. "Positive associations between ACTL8 and the progression of colorectal cancer (CRC), head and neck squamous cell carcinoma (HNSCC), and non-small-cell lung cancer (NSCLC) have also been reported." (PMID 39857819, 2025).
lung carcinoma (1 paper, 2022). "Actin like 8 (ACTL8) is highly expressed not only in lung cancer but also in various other types of tumours." (PMID 35574342, 2022). "ACTL8-knockdown inhibits lung cancer cell proliferation, colony formation, cell cycle progression, migration and invasion, and lung cancer cell A549 tumour growth in vivo, indicating that it exerts an oncogenic role in lung cancer cell tumorigenesis and progression." (PMID 35574342, 2022).
tumor (6 papers, 2015 to 2025). "The highest average expression values, calculated across all cancer samples, have candidate tumor-specific antigens ACTL8 (ranked 2nd), MAGEA6 (ranked 14th) and C6orf15 (ranked 8th) with a normalized count expression of 2167.8, 981.4 and 787.0 respectively." (PMID 31069014, 2019). "Several studies have suggested that ACTL8 is immune-related and could be a potential target for tumor immunotherapy." (PMID 39857819, 2025). "Regarding the top-3 tumor-specific antigens, remaining PPAEs are salivary gland for targeting CT83 and colon for targeting ACTL8." (PMID 31069014, 2019). "In the present study, a signature for BRCA radiotherapy sensitivity prediction was developed based on the expression of six characteristic DEGs, including HOXB13, NKX2-2, ADAMTS20, LOC284930, ACTL8 and LOC101928978, in BRCA tumor samples compared with their paracancerous samples for the first time." (PMID 33179733, 2020).
cancer (5 papers, 2013 to 2025). A tumor composed of atypical neoplastic, often pleomorphic cells that invade other tissues. "Interestingly, aberrant expression of ACTL8, a cancer/testis antigen gene, is reported to associate with stem cell-like enrichment and an EMT signature, both of which are characteristics of DSRCT." (PMID 30486883, 2018). "ACTL8 is a member of the cancer/testis antigens (CTA) family." (PMID 39857819, 2025). "More interestingly, due to the high immunogenicity and specificity of CTAs in cancer, several CTAs, including CT45, BCAP31 and ACTL8, have been targeted for developing novel therapeutics against cancer." (PMID 35574342, 2022).
ACTL8 also shares sentences with these, for which no sentence is quoted: glioblastoma (3 papers); estrogen-receptor negative breast cancer (1); head and neck squamous cell carcinoma (1); non-small cell lung carcinoma (1); pancreatitis (1).